KRAS (KRas proto-oncogene, GTPase)
Diseases named in the same sentence as KRAS in open-access papers (continued):
Sharing a sentence is not in itself a finding about the gene and the disease.
cancer (6,040 papers, 1991 to 2026). A tumor composed of atypical neoplastic, often pleomorphic cells that invade other tissues. "In our case, we use an RNA sequence corresponding to KRAS G12V, a prominent mutation found in many human cancers." (PMID 41495895, 2026). "Ras proteins are prominent oncogenes, with KRas mutations found in approximately 80% of cancer cells harboring Ras mutations." (PMID 42054419, 2026). "Regarding KRAS, STK11 mutation is significantly enriched in KRAS G12C-mutated tumors compared to KRAS non-G12C-mutated tumors (20.59% vs. 5.95%, [OR] = 4.10) across all cancer types, indicating their potential relationship." (PMID 41541668, 2026). "In summary, we analyzed the alternative splicing patterns of KRAS E4 across 33 cancer types and found that a subset of cancer tissues expressed KRAS4A splicing variants at higher levels than KRAS4B splicing variants." (PMID 41368203, 2026). "To elucidate the regulatory mechanism underlying the alternative splicing of KRAS E4 in cancer tissues, we focused on the expression patterns of splicing factors." (PMID 41368203, 2026). "KRAS is a well-established oncogene that exhibits high-frequency mutations at cancer-driver hotspot loci across human cancers." (PMID 41368203, 2026). "For example, the missense KRAS mutations G12D and G12V are frequent in all KRAS-driven cancers, but G12R and G12C substitutions are very prevalent only in pancreatic (~15-20%) and lung (~60%) adenocarcinomas, respectively." (PMID 41266617, 2026). "Mutation-induced drug resistance is a major contributor to the failure of targeted cancer therapies, particularly in tumors driven by mutations in the KRAS oncogene." (PMID 41993311, 2026). "KRAS is one of the most frequently mutated genes in all human cancers, and its oncogenic mutation hotspots are glycine 12 (G12), glycine 13 (G13), glutamine 61 (Q61) and alanine 146 (A146)." (PMID 41750275, 2026). "Somatic mutations of the KRAS gene at hotspot codons are well-established drivers of cancer development." (PMID 41368203, 2026). "Comparative and functional studies using this platform, human cohorts and mice identified core principles underlying tissue-specific evolution of KRAS-initiated cancers." (PMID 41741657, 2026). "Although direct KRAS inhibitors have shown significant success in other cancers, the specific KRAS mutation variants that are prevalent in PDAC have proven largely resistant to such targeted approaches." (PMID 40572765, 2025). "Consistent with this key regulatory role, activating mutations of RAS are present in ~20% of human cancers, with the majority occurring in the KRAS isoform." (PMID 38328115, 2025). "The detection of KRAS mutations, among the most frequent genetic alterations in human cancers such as colorectal, pancreatic, and lung adenocarcinomas, constitutes a cornerstone of molecular oncology." (PMID 41514544, 2025). "Targeted sequencing analysis of cancer-related genes revealed the somatic KRAS c.182A>G (p.Gln61Arg) variant in frozen affected tissue of one patient." (PMID 40904803, 2025). "This study investigates how specific KRAS mutations disrupt protein interactions to rewire cancer cell metabolism." (PMID 40427667, 2025).
cancer (continued). "The well-known proto-oncogene KRAS is one of the most frequently mutated genes in various cancers and the overexpression of KRAS can result in poor survival." (PMID 40725120, 2025). "The Kirsten Rat Sarcoma (KRAS) gene mutation is the most prevalent mutation across all cancers, including PC." (PMID 41200180, 2025). "The GTPase KRAS (Kirsten rat sarcoma viral oncogene homolog) is a critical oncogene that is somatically mutated in approximately 10% of all human cancers, with particularly high prevalence in certain malignancies." (PMID 40563459, 2025). "Sotorasib (AMG510) is the first irreversible, covalent, and selective inhibitor of KRAS G12C-mutated cancers." (PMID 40756996, 2025). "The biological principle involves exploiting specific vulnerabilities induced by KRAS G12C mutation in cancer cells." (PMID 40940900, 2025). "Metabolic changes in KRAS mutation towards anabolic pathways are crucial for cancer cell proliferation in PDAC." (PMID 40805153, 2025). "These vaccines aim to stimulate the immune system to recognize and attack cancer cells harboring specific neoantigens that are associated with KRAS mutations, such as G12D, G12V, or G12C." (PMID 40361439, 2025). "Ras is the most frequently mutated oncogene in cancer, occurring in about 19% of all cancers, with KRAS being the most commonly mutated isoform." (PMID 40943615, 2025). "One of the most frequent carcinogenic chemicals is methyl nitrosourea, which targets the second base on the 12th codon of HRAS and KRAS, generating a G12D mutation in many cancer types." (PMID 40002297, 2025). "In the phase I/II KRYSTAL-1 study on 116 cancer patients carrying KRAS G12C mutations, 42.9% demonstrated confirmed objective responses, with a median duration of 8.5 months, progression-free survival of 6.5 months, and overall survival reaching 12.6 months." (PMID 39820726, 2025). "For many years, KRAS was considered an undruggable target; however, recent advancements have led to the development of selective inhibitors for KRAS G12C mutations, making it possible to target mutant KRAS cancers." (PMID 40909947, 2025). "The prominence of G12R mutations in PDAC contrasts strikingly with other cancers that harbor high levels of KRAS mutations; G12R mutations are found in only 1%–2% of NSCLC and CRC." (PMID 40829181, 2025). "KRAS mutations are among the most frequently observed genetic alterations across a wide range of human cancers." (PMID 41294676, 2025). "So, in cancer cells with mutated KRAS genes, the GTPase activity and GAPs’ responsiveness to K-RAS protein become impaired, allowing a swift exchange of guanosine diphosphate (GDP) for GTP and allowing K-RAS to remain active in cancer cells." (PMID 39181121, 2025). "This case underscores the complexity of managing NSCLC with coexisting EGFR and KRAS mutations and highlights the importance of continuous molecular monitoring to adapt treatment strategies as the cancer evolves." (PMID 39852181, 2025). "KRASG12C selective inhibitors, such as sotorasib and adagrasib, have raised hopes of targeting other KRAS-mutant alleles in patients with cancer." (PMID 39711431, 2025). "The vaccine delivers two separate mRNAs: the first encodes a collection of peptide epitopes, while the second encodes epitopes specifically derived from common cancer hotspot mutations, such as KRAS G12 or G13." (PMID 41586257, 2025). "Similar to the findings in KRAS-mutant cancers, the proteasome inhibitor MG132 rescued the loss of SOS1 upon SIAIS562055 treatment." (PMID 39437162, 2025). "Despite being the most frequently mutated and activated oncogene in various cancers, targeting KRAS has posed a great therapeutic challenge over the past 50 years since its discovery." (PMID 39960727, 2025). "KRAS mutations serve as the genes most associated with the alterations and genetic events that cause PDACs, appearing in over 90% of cancers." (PMID 40075634, 2025).
cancer (continued). "ELI-002 incorporates either two (ELI-002 2P) or seven (ELI-002 7P) KRAS-mutated Amph-peptides and is currently being investigated as a cancer vaccine in patients with solid tumors harboring KRAS mutations (NCT04853017, NCT05726864)." (PMID 40495154, 2025). "In this model, KRAS mutations act as initiating events, requiring a longer latency and the accumulation of additional genetic alterations before clinical cancer develops." (PMID 41439081, 2025). "It firstly provides an overview of fundamental KRAS biology within the cell signalling landscape and how KRAS mutations are associated with cancer pathogenesis." (PMID 39820726, 2025). "As one of the most frequently mutated oncogenes, KRAS was long deemedundruggable, posing a significant challenge for targeted cancer therapy." (PMID 41394580, 2025). "Despite the progress in KRAS G12C inhibitors, they fail to target other KRAS mutants that accounts for more frequent KRAS mutations in cancer patients." (PMID 39820726, 2025). "We report here the preclinical evaluation of glecirasib, which efficiently inhibited the growth of a panel of KRAS p.G12C–mutated cancer cells by inducing cell-cycle arrest and apoptosis and showed favorable selectivity against wild-type (WT) KRAS." (PMID 40304209, 2025). "Those discoveries led to the integration of KRAS mutation analysis into cancer diagnostics and therapeutics." (PMID 41514544, 2025). "Benign and malignant tumors were diagnosed with equal frequency in both genetic groups, but renal tumors were strongly associated with KRAS mutations." (PMID 41438146, 2025). "Oncogenic KRAS mutation is a powerful driver for various cancers and exists in nearly 30% of LUAD74." (PMID 41208901, 2025). "KRAS mutations enable cancer cells to proliferate by maintaining a higher proportion of KRAS in the active GTP-bound state." (PMID 40779492, 2025). "KRAS mutations have been shown to exert transformative capacity in aggressive cancers by hyperactivating various downstream signaling pathways, such as the MAPK and PI3K/AKT pathways." (PMID 40091835, 2025). "Identifying more functionally avid TCRs targeting KRAS mutations will expand the number of patients potentially eligible for TCR-based therapeutics for patients with mutant KRAS–positive cancers." (PMID 39846249, 2025). "For instance, Kirsten rat sarcoma viral oncogene homolog (KRAS) is one of the most frequently mutated proto-oncogenes found in cancers and encodes a small GTPase belonging to the RAS protein family." (PMID 40663150, 2025). "Oncogenic mutations in the KRAS gene are a hallmark of many cancer types, including a subset of NSCLC." (PMID 39782689, 2025). "Utilizing the immune system to target cancer cells with KRAS mutations specifically has the potential to overcome resistance mechanisms and improve the effectiveness of treatment." (PMID 40075634, 2025). "Our detailed RNA-seq analysis showed that all three antibiotics downregulated hallmark EMT and KRAS signaling pathways, both of which are central to cancer cell plasticity and invasiveness." (PMID 40847193, 2025). "A study evaluating 504 patients with diverse cancers found that KRAS mutations were present in 38% of patients with PIK3CA mutations compared with 16% of patients with wild-type PIK3CA (P = 0.001)." (PMID 39808497, 2025). "The elevated rates of protein synthesis and rapid protein turnover required by KRAS-activating mutations in cancer cells lead to a greater dependence on the proteasome system, which is crucial for maintaining protein homeostasis through degradation." (PMID 40091835, 2025). "These large-scale screens can be used to identify vulnerabilities that are selectively essential for certain mutational subtypes (such as BRAF or KRAS mutated cancers), or to nominate candidate targets selectively required for cancer types of interest." (PMID 40804185, 2025).
cancer (continued). "GOT1 was crucial for the metabolic adaptation of cancer cells, particularly in those harboring KRAS mutations, where it coordinated glycolysis and oxidative phosphorylation pathways to support cell proliferation." (PMID 40390008, 2025). "Understanding the prevalence and role of KRAS gene mutations is crucial for unraveling the genetic basis of these cancers and developing targeted therapies that effectively exploit these mutations." (PMID 40906088, 2025). "In adenomyotic epithelium, we identified somatic mutations in cancer-associated genes such as KRAS (34.1%), PIK3CA (12.2%), ARID1A (12.1%), and FBXW7 (9.8%) with high mutant allele frequency." (PMID 40679511, 2025). "Despite improved treatment regimes using targeted therapy and checkpoint inhibitors, cellular immunotherapy options for KRAS-mutated cancers remain elusive." (PMID 40794198, 2025). "Overall, 20–50% of KRAS-mutated cancers carry a G12D mutation, including 50% of ampullary carcinoma, 48% of appendiceal adenocarcinoma and 44% of cholangiocarcinoma." (PMID 40430514, 2025). "KRAS mutations induced mutated KRAS proteins structurally in active form, leading to continuous cancer cells proliferation." (PMID 40361506, 2025). "Mutations in the RAS signaling pathway, especially in the KRAS oncogene, are major drivers of cancer progression, therapy resistance, and poor clinical outcomes." (PMID 41514544, 2025). "Macropinocytosis is a form of endocytosis that allows cells to engulf extracellular fluid and molecules, which is often upregulated in cancer cells with certain mutations, including KRAS mutations." (PMID 40501736, 2025). "KRAS mutations frequently occur in multiple cancers including CRC and PDAC, functioning as a ‘‘molecule switch’’ determining the activation of various oncogenic signaling pathways." (PMID 40165901, 2025). "Kirsten rat sarcoma viral oncogene homolog (KRAS) is the most frequently mutated oncogene in human cancer, with a mutation rate of approximately 32% among LUAD patients and 88% in pancreatic adenocarcinomas." (PMID 40890128, 2025). "Oncogenic mutations of RAS, particularly KRAS, are found in a significant proportion of human cancers, including gastrointestinal (< 50%), pancreatic (13.37%), and lung (12.75%) cancers." (PMID 40597785, 2025). "Future research should focus on developing RASON-targeting approaches, investigating its role in other KRAS mutations and cancer types, and exploring its potential to enhance responses to immunotherapies." (PMID 40128846, 2025). "KRAS mutations significantly rewire cellular metabolic processes to meet the increased energy demands of cancer cells." (PMID 39806421, 2025). "KRAS mutations are now recognized as pivotal drivers across multiple cancer types, with codon 12 (G12) mutations—particularly G12C, G12D, and G12V—representing the most frequent oncogenic variants." (PMID 40427667, 2025). "The study of lipid metabolism has gained significant attention, particularly regarding its interplay with KRAS mutations in cancer." (PMID 39806421, 2025). "Aziridines have also gained attention in selective binding with KRAS mutated proteins, which promote uncontrolled cell growth and potentially lead to cancer." (PMID 40844185, 2025). "In summary, this study identifies REGγ as a KRAS-associated vulnerability that promotes pan-KRAS–mutant cancer progression." (PMID 40091835, 2025). "This variation in activation levels across KRAS mutation subtypes contributes to differing biological outcomes and highlights the need for precise subtyping in KRAS-driven cancers." (PMID 40611261, 2025). "Genomic analysis of cancer patient samples has indicated that high-level amplification of KRAS G12C allele is also associated with resistance to KRAS G12C inhibitor." (PMID 40597785, 2025). "In conclusion, we report the synergistic effect of the natural alkaloid camptothecin and the KRAS inhibitor, sotorasib, in KRAS-mutated cancer cells." (PMID 40756996, 2025).
cancer (continued). "We observed a synergistic relationship between camptothecin and sotorasib in KRAS-mutated cancer cells." (PMID 40756996, 2025). "Self-funded molecular testing I had arranged and paid for, identified a KRAS G12D mutation, and I was fortunate enough to meet a cancer trials team that had a tumor-agnostic clinical trial targeting this mutation across different cancer types." (PMID 41237268, 2025). "REGγ depletion led to growth arrest in all tested cell lines; however, compared with their wild-type counterparts, cancer cells harboring pan-KRAS mutations exhibited a higher sensitivity to REGγ inhibition." (PMID 40091835, 2025). "KRAS mutations are among the most frequent oncogenic alterations in human cancers, particularly in pancreatic, colorectal, and lung adenocarcinomas." (PMID 41459907, 2025). "Several studies and outcomes of clinical trials have shown that cancer cells can overcome KRAS mutation inhibition in a KRAS-independent manner." (PMID 40597785, 2025). "KRAS codon G12 is the most frequently mutated site in human tumors, accounting for approximately 90% of KRAS mutations and 12% of all cancer patients." (PMID 40611261, 2025). "KRAS mutation-mediated signaling enhances cancer cell competitiveness and reduces therapeutic susceptibility by increasing glucose uptake and hexokinase activity, promoting pathways such as glycolysis, the TCA cycle, and PPP." (PMID 39970873, 2025). "To understand this observation further, we analyzed data from The Cancer Genome Atlas (TCGA) Pan-Cancer Atlas, which verified a significant co-occurrence of KRAS and PIK3CA mutations in CRC." (PMID 39808497, 2025). "In current clinical applications, macropinocytosis, a non-selective endocytic pathway, is being widely explored for the delivery of anti-cancer drugs, especially in KRAS-mutated cancers (e.g., lung cancer), and shows significant potential." (PMID 40723808, 2025). "KRAS is the most mutated oncogene in human cancer, occurring in 13% of NSCLC, and it encodes guanosine triphosphatase, which regulates signal transduction." (PMID 40729346, 2025). "A significant proportion of human cancers have mutations in one of the RAS genes, with KRAS mutations being particularly common in certain cancers." (PMID 39786607, 2025). "KRAS mutations show tumor type-specific patterns, with G12D and G12V being the most frequent among cancers, but they vary in frequency." (PMID 40075634, 2025). "SiRNA-based therapeutics targeting KRAS mutations and cancer vaccines have emerged as a viable cancer treatment method." (PMID 41374970, 2025). "Conversely, certain cancer cells harbouring oncogenic KRAS mutations exhibit elevated levels of SLC7A11 expression along with intracellular cysteine and GSH abundance." (PMID 39354653, 2025). "Here, we review the history of KRAS-targeted therapy, highlighting existing challenges, and summarize changes in the immune microenvironment of KRAS-mutated cancers and their potential therapeutic targets." (PMID 40611261, 2025). "This will enable the development of more effective and precise treatments for cancers associated with KRAS mutations." (PMID 39820726, 2025). "The clinical study of KRAS is of great importance with respect to cancers, somatic GOF mutations in this gene are often observed in about 25% of cancers affecting humans." (PMID 38376733, 2025). "Camptothecin is a natural alkaloid isolated from Camptotheca acuminata, which has been extensively reported for its significant potential to induce DNA damage, leading to apoptosis-mediated cell death in KRAS-mutated cancers." (PMID 40756996, 2025). "Activating KRAS mutations have been associated with various human cancers, including lung adenocarcinoma and colorectal and pancreatic carcinomas." (PMID 40362524, 2025).